RNU6-887P (RNA, U6 small nuclear 887, pseudogene)
Gene: Small nuclear RNA gene on chromosome 4 (39,399,149 to 39,399,248, forward strand). Ensembl gene ENSG00000222592.
Homologues: Orthologues: chimpanzee U6 (97% identical), macaque U6 (96% identical), pig U6 (78% identical). Paralogues in human: RNU6-1152P (86% identical), RNU6-657P (85% identical), RNU6-1060P (84% identical), RNU6-1181P (84% identical), RNU6-15P (84% identical), RNU6-19P (84% identical), RNU6-211P (84% identical), RNU6-41P (84% identical), RNU6-44P (84% identical), RNU6-536P (84% identical), RNU6-589P (84% identical), RNU6-820P (84% identical), and 1284 more.